SIRT2 (sirtuin 2)
Diseases named in the same sentence as SIRT2 in open-access papers (continued):
Sharing a sentence is not in itself a finding about the gene and the disease.
colorectal cancer (continued). "Experimentally, SIRT2 is reported to be targeted by miR-212-5p (which is expressed from the 5′ end of the miR-212 precursor) in human colorectal cancer (CRC) via its 3′-UTR, leading to posttranscriptional downregulation of SIRT2." (PMID 34943825, 2021). "To determine whether SIRT2 is involved in SAC functions, we used the colorectal cancer cell line HCT116 (a mitotic checkpoint-proficient near-diploid cell line), which is commonly employed for studies of SAC, autophagy, and SIRT2 functions." (PMID 27213315, 2016). "Our findings provide insight into the important role of SIRT2 in colon tumour angiogenesis and suggest that SIRT2/STAT3/VEGFA might be a novel prognostic biomarker and a potential therapeutic target for patients with colorectal cancer." (PMID 30584257, 2018). "Unlike SIRT2 and SIRT4, in the colorectal cancer, SIRT1 was reported to participate in the tumorigenesis, and its expression is positively correlated with the cancer progression in clinic." (PMID 35217651, 2022).
diabetes (20 papers, 2014 to 2025). "The MED group showed an increase in bilirubin and five of its degradation products, which is negatively associated with diabetes, and in the cytokine SIRT2 that inhibits gluconeogenesis." (PMID 37666816, 2023). "While abundant data point to the essential role of SIRTs activities, there are genetic polymorphisms of SIRT1 and SIRT2 concerning diabetes." (PMID 30559718, 2018). "SIRT2 participates in metabolic pathways through various signalling pathways and is associated with the occurrence of nervous system-related degenerative diseases, various tumours, diabetes, and cardiovascular diseases." (PMID 36101744, 2022). "Genetic polymorphism of SIRT2 has been reported to associate with diabetes development." (PMID 33754030, 2021). "Moreover, genetic polymorphisms of SIRT1 and SIRT2 have been reported to associate with diabetes development." (PMID 30559718, 2018). "Thus, SIRT2 may be a novel molecular target for diabetes therapy and may thus shed light on the underlying diabetes treatment mechanisms of sirtinol." (PMID 28127057, 2017). "Thus, SIRT2 may be a novel molecular target for diabetes therapy, and may shed light on the underlying diabetes treatment mechanism of sirtinol." (PMID 28127057, 2017). "The fact that SIRT2 was not only elevated in diabetes but further increased in the nephropathy group indicates that this biomarker is specifically associated with renal involvement rather than diabetes alone." (PMID 41303131, 2025). "Altogether, these findings establish SIRT2 as a promising therapeutic target for safely increasing β cell numbers in diabetes." (PMID 40762838, 2025). "Nicotinamide riboside promotes Mfn2-mediated mitochondrial fusion via the SIRT2-PGC1α-PPARα pathway, reduces diabetes-induced cardiomyocyte apoptosis, and prevents diabetes-induced cardiac insufficiency." (PMID 37670891, 2023). "Further investigation indicated that restoring SIRT2 expression attenuated maternal diabetes-induced NTDs, suggesting that SIRT2-induced MARCKS deacetylation exerts a protective effect on neuroepithelial cells through the inhibition of MARCKS phosphorylation." (PMID 30655546, 2019). "SIRT1 activators will exert their activity protecting individuals from diabetes, while inhibition of SIRT2 would protect dopaminergic cell against death both in vitro and in a drosophila model of PD." (PMID 24465703, 2014). "Given the here-described role of SIRT2 in restraining adaptive β cell proliferation, this work opens the possibility of therapeutically targeting SIRT2 for controlled and selective β cell expansion in diabetes." (PMID 40762838, 2025). "SIRT2 downregulation-induced histone acetylation may be involved in diabetes-induced neural tube defects (NTDs)." (PMID 39861104, 2025). "Although the role of SIRT2 in diabetes is currently controversial, undoubtedly, SIRT2 may be a novel molecular target for future diabetes treatment." (PMID 36101744, 2022). "Recently, it has been shown that Sirt2 and Sirt6 are involved in diabetes-induced NTDs." (PMID 28798665, 2017). "Therefore, SIRT2 can be involved in metabolic disorder-related inflammation and oxidative stress, thereby triggering the occurrence of metabolic disorder-related diseases, such as neurodegenerative diseases, tumours, diabetes, and cardiovascular diseases." (PMID 36101744, 2022). "After adjustment for age, sex, diabetes mellitus, hypertension, cognitive status (MMSE scores), and number of co morbidities, serum SIRT1, SIRT2, and SIRT3 concentrations were found to be significantly lower in frail as compared to nonfrail patients." (PMID 25100619, 2014). "Having validated islet-specific Sirt2 inactivation with the GLP1-Sirt2 ASO, we asked whether the ASO enhances β cell proliferation in preclinical models of diabetes." (PMID 40762838, 2025).
diabetes (continued). "Irrespective of various categories such as differences in age (>60), sex, diabetes mellitus, hypertension, and number of comorbidities, the SIRT1 and SIRT3 levels were still significantly lower in case of frail as compared to nonfrail; however, in case of SIRT2, the differences were not significant." (PMID 25100619, 2014).
Sepsis (20 papers, 2016 to 2026). Sepsis is defined as life-threatening organ dysfunction caused by a dysregulated host response to infection. "We have reported that ethanol-induced increase in SIRT2 represses immune response and bacterial clearance, while SIRT2 deficiency is associated with increased bacterial clearance and decreased mortality in ethanol with sepsis-mice." (PMID 36865524, 2022). "We have also shown the effect of SIRT2 deficiency on sepsis response in vivo in lean mice previously." (PMID 36865524, 2022). "We show that similar to ob/ob mice, the hypo-inflammatory phase of DIO mice with sepsis is also associated with increased SIRT-2 expression and SIRT-2 inhibition during the hypo-inflammatory phase reverses it." (PMID 27500833, 2016). "In obese-sepsis mice, the exaggerated hyper-inflammation is associated with decreased SIRT2 levels, whereas prolonged hypo-inflammation is associated with a sustained increase in SIRT2 expression." (PMID 35052507, 2021). "We have also shown that SIRT2 knock out mice exhibit increased microvascular inflammation, while SIRT2 overexpression is associated with decreased microvascular inflammation hyper-inflammatory phase in sepsis mice." (PMID 30216989, 2018). "First we studied whether the hypo-inflammatory phase of sepsis in DIO mice with sepsis is associated with increased SIRT2 expression." (PMID 27500833, 2016). "We have reported previously, that decreased pathogen clearance and increased mortality in ethanol-drinking mice with sepsis occur via increased expression of sirtuin 2 (SIRT2)." (PMID 36865524, 2022). "Previously, we reported that ethanol with sepsis decreases 7-day survival with inability to clear pathogen in mice via increased SIRT2 expression." (PMID 36865524, 2022). "We reported that the ethanol-exposure suppresses innate-immune response, pathogen clearance, and decreases survival in sepsis-mice via sirtuin 2 (SIRT2)." (PMID 36865524, 2022). "Here, we treated Ethanol-exposed WT mice with SIRT2-specific inhibitor AK-7 (40mg/kg intraperitoneally, once) and induced polymicrobial sepsis using intraperitoneal injection of cecal slurry." (PMID 36865524, 2022). "The role of SIRT2-Bmal1 interactions and their effect on immune and metabolic functions of macrophages during sepsis remain to be elucidated." (PMID 36865524, 2022). "We have shown differential roles of SIRT1 and SIRT2 in sepsis in a biological context-dependent manner previously." (PMID 36865524, 2022). "Specifically, SIRT2 expression is critical for prolonged hypo-inflammation in obese mice with sepsis, and SIRT2 inhibition in ob/ob mice during the hypo-inflammatory phase of sepsis reverses hypo-inflammation and improves survival." (PMID 33810233, 2021). "For example, SIRT2 inhibits inflammation in animal models of collagen‐induced arthritis, sepsis, or colitis." (PMID 32515550, 2020). "Other recent reports demonstrate that SIRT2 can repress the inflammatory response via deacetylation and inhibition of NF‐kB, using transgenic (SIRT2‐/‐) mice, in models of sepsis or colitis." (PMID 32515550, 2020). "SIRT2 inhibition using AK-7 compound during the hypo-inflammatory phase of obese mice with sepsis reversed hypo-inflammation via activation of immune cells and endothelial cells, as well as improved survival." (PMID 30216989, 2018). "While SIRT2 modulates sepsis inflammation, sepsis inflammation and oxidative stress also regulate SIRT2." (PMID 30216989, 2018). "We further highlight the role of SIRT1 and SIRT2 as potential “druggable” targets for promoting immunometabolic homeostasis and increasing sepsis survival." (PMID 30216989, 2018). "This study suggested that SIRT2 plays an important role in the regulation of microvascular inflammation in early sepsis." (PMID 30533222, 2018). "In obese mice with sepsis, increased SIRT2 protein levels prolong hypo-inflammation instead; SIRT2 is the most abundant of sirtuins in the adipose tissue." (PMID 30216989, 2018).
Sepsis (continued). "Although the involvement of SIRT2 in oxidative stress, inflammation, microglial activation, macrophage polarization and during sepsis have been studied, the role of SIRT2 in bacterial pathogenesis yet remains largely elusive." (PMID 30452468, 2018). "We have shown previously that in fact the AK-7, a SIRT2 inhibitor treatment during the immunosuppressive phase of sepsis in obese mice improved survival." (PMID 28503576, 2017). "Together, the data support that SIRT2 regulates microvascular inflammation: low SIRT2 increases and high SIRT2 decreases leukocyte/platelet adhesion in sepsis by controlling ICAM-1 and E-selectin expression." (PMID 28503576, 2017). "The clinical significance of this in mouse sepsis is that sepsis mortality is affected by the SIRT2 modulation as well." (PMID 28503576, 2017). "Mechanistically, in the sepsis cell model, SIRT-2 expression modulated inflammatory response by deacetylation of NFκBp65." (PMID 27500833, 2016). "Here, we investigated the role of sirtuins, especially the adipose-tissue abundant SIRT-2 on transition from early to late sepsis in obese with sepsis." (PMID 27500833, 2016). "There was a marked increase in the SIRT-2 expression small intestinal tissue in DIO mice with sepsis during the hypo-inflammatory phase of sepsis." (PMID 27500833, 2016). "Specifically, we report for the first time to our knowledge, that SIRT-2 modulates sepsis-related inflammation in obese -septic mice." (PMID 27500833, 2016). "SIRT-2 inhibition in ob/ob mice during the hypo-inflammatory phase of sepsis reversed the repressed microvascular inflammation in vivo via activation of endothelial cells and circulating leukocytes and significantly improved survival." (PMID 27500833, 2016). "In our sepsis cell model, we show that SIRT-2 deacetylates master inflammatory and immune transcription factor NFkB p65, which is known to repress transcription of inflammation and immune activator genes, like TNF-α, IL-6 etc.." (PMID 27500833, 2016). "We confirmed the key finding of the role of SIRT2 during hypo-inflammatory phase of sepsis in this project in DIO-sepsis mice." (PMID 27500833, 2016). "We also studied the SIRT2 expression in WT mice with sepsis during corresponding time points (6 and 24 hours post-sepsis) and show in supportive information S2B Fig that in WT mice, the SIRT2 expression remained unchanged at 6 vs. 24 hours post-sepsis." (PMID 27500833, 2016). "Since current animal studies have shown that deletion of Sirtuin 2 gene restores macrophage immune functions, especially phagocytosis, it is suggested that Sirt2 inhibition strategies should be applied at an early stage of sepsis." (PMID 40379629, 2025). "Similarly, a cross talk between SIRT1 and SIRT2 during acute ethanol-induced immunosuppression in ethanol with sepsis, needs evaluation." (PMID 36865524, 2022). "Genetic deficiency or pharmacological inhibition of SIRT2 reverse PFKP-deacetylation, suppressed LC3-activation and phagocytosis including LAP, in ethanol-exposed macrophages to improve bacterial clearance and survival in ethanol with sepsis mice." (PMID 36865524, 2022). "Ethanol exposure increased SIRT2 expression and reduced the inflammatory response to sepsis." (PMID 34155309, 2021). "We showed both SIRT1 and SIRT2 deacetylate NFκB p65 subunit in sepsis." (PMID 35052507, 2021). "Although less described, SIRT2 also plays a role in macrophage biology, as SIRT2 ameliorates LPS-induced iNOS expression in bone marrow macrophages and its activities are required for the hypo-inflammation phase of sepsis in a mouse model." (PMID 31799621, 2020). "SIRT2 has been shown to regulate immuno-metabolism in sepsis." (PMID 32697192, 2020). "We observed that, instead, SIRT2 expression increased in obese mice with sepsis hypo-inflammation." (PMID 30216989, 2018). "Evidence suggests that SIRT2 knock out mice show increased bacterial clearance in sepsis." (PMID 30216989, 2018).
Sepsis (continued). "However, SIRT5 showed opposite expression patterns and functions compared with SIRT1 and SIRT2 in a sepsis model involving macrophages." (PMID 30533222, 2018). "In this project, we studied the role of SIRT2 on sepsis-related inflammation." (PMID 28503576, 2017). "Here, we report a role for SIRT2 in inflammation during early sepsis." (PMID 28503576, 2017). "We determined SIRT-2 expression during different phases of sepsis." (PMID 27500833, 2016). "However, another study found that, in fatal septic shock mice models, AGK2 (a selective SIRT2 inhibitor) administration significantly improved the survival rate of mice and decreased sepsis-related “cytokine storm” coagulopathy disorders and bone marrow atrophy." (PMID 30533222, 2018). "Considering that SIRT2 impacted phagocytosis but not cytokine expression, we hypothesized that SIRT2 deficiency should provide some benefit during chronic lethal infection but not fulminant sepsis, and should not sensitize to benign infection." (PMID 28894448, 2017). "Thus, SIRT2 inhibition maybe a potential therapeutic option in alcohol with sepsis." (PMID 36865524, 2022). "We also show that SIRT2 inhibitor AK-7 reverses dysregulated phagocytosis and LAP and improves sepsis survival in mice." (PMID 36865524, 2022). "We show that the SIRT2 inhibitor AK-7 reverses repressed LAP, improves peritoneal bacterial clearance and improves survival in ethanol with sepsis mice." (PMID 36865524, 2022). "In contrast with SIRT1 and SIRT2, SIRT5 expression is decreased during the hypo-inflammatory phase of sepsis." (PMID 30216989, 2018). "SIRT2 knockin mice showed decreased E-selectin and ICAM-1 levels, following attenuation of cellular adhesion with sepsis in the small intestine, as well as an improved 7-day survival rate." (PMID 30533222, 2018). "In conclusion, the study, for the first time to our knowledge, supports a critical role for SIRT2 in regulating MVI responses and in influencing sepsis mortality in mice." (PMID 28503576, 2017). "Since SIRT-2 expression appears to be increased in ob/ob mice with CLP25.2, we tested the effects of SIRT-2 specific inhibitor AK-7 on 7-day sepsis survival and observed there was a significant increase in survival of ob/ob septic mice treated with AK-7." (PMID 27500833, 2016). "The effect of SIRT2 modulation on microvascular inflammation during early sepsis is not very well studied." (PMID 28503576, 2017). "e. decreased SIRT-1 and increased SIRT2 expression during the hypo-inflammatory phase in the liver tissue of ob/ob mice with sepsis (not shown)." (PMID 27500833, 2016). "Besides, the oxidation of cysteine on SIRT6 and SIRT2 as well as the nitrosylation of SIRT1 could decrease their expression, respectively, during sepsis." (PMID 30533222, 2018). "Using a genetic approach to modulate SIRT2 in mice, we show that in early sepsis, low SIRT2 levels enhance and high SIRT2 levels attenuate the MVI inflammatory response in vivo via modulation of adhesion molecule expression impact sepsis mortality rates in rodent sepsis." (PMID 28503576, 2017). "In contrast, the role of SIRT2 in sepsis-induced AKI appears to be detrimental, as the absence of SIRT2 improves renal function and reduces tubular injury." (PMID 40218970, 2025). "Unlike SIRT1 and SIRT2, SIRT3 activation and overexpression show several positive effects in sepsis treatment." (PMID 30533222, 2018). "Thus, SIRT-2 and not SIRT-1 expression was increased during hypo-inflammatory phase of ob/ob-sepsis mice." (PMID 27500833, 2016). "Thus, the data suggest that SIRT-2 and not SIRT-1 plays a crucial role in ob/ob mice with sepsis." (PMID 27500833, 2016).